TFF2 (trefoil factor 2)
Diseases named in the same sentence as TFF2 in open-access papers (continued):
Sharing a sentence is not in itself a finding about the gene and the disease.
colorectal cancer (7 papers, 2010 to 2021). A primary or metastatic malignant neoplasm that affects the colon or rectum. "In conclusion, the research showed that PAR4 and TFF2 expression were frequently up-regulated in colorectal cancer and the increased expression was associated with the clinically aggressive phenotype." (PMID 25876034, 2015). "Association between the mRNA levels of PAR4 and TFF2 with clinical pathological data of colorectal cancer." (PMID 25876034, 2015). "Association between the protein levels of PAR4 and TFF2 with clinic-pathological data of colorectal cancer." (PMID 25876034, 2015). "Next, we examined the levels of PAR4 and TFF2 mRNA in 38 colorectal cancer samples by real-time PCR." (PMID 25876034, 2015). "In this study, the expression level of PAR4 and TFF2 in colorectal cancer tissues was measured using real-time PCR (n = 38), western blotting (n=38) and tissue microarrays (n = 66)." (PMID 25876034, 2015). "The majority of PAR4 and TFF2 in colorectal cancer tissues are localized in the cytoplasm as shown by Immunostaining." (PMID 25876034, 2015). "The colorectal carcinoma cell LoVo showed an increased response to TFF2 as assessed by cell invasion upon PAR4 expression." (PMID 25876034, 2015). "Taken together, the results demonstrated that the up-regulated expression of PAR4 and TFF2 frequently occurs in colorectal cancer tissues, and that overexpression of PAR4 may be resulted from promoter hypomethylation." (PMID 25876034, 2015). "Furthermore, the majority of PAR4 and TFF2 staining in malignant colorectal cancer samples were localized in the cytoplasm." (PMID 25876034, 2015). "We also showed PAR4 promoted colorectal cancer cells’ invasion in respond to TFF2." (PMID 25876034, 2015). "TFF2 has been verified to promote cell migration via PAR4, but the roles of PAR4 and TFF2 in the progress of colorectal cancer are still unknown." (PMID 25876034, 2015). "TFF2 expression was up-regulated in 46 (69.7%) colorectal cancer samples." (PMID 25876034, 2015). "However, after intervention of PAR4 expression, PAR4 positive colorectal carcinoma cell HT-29 was less responsive to TFF2 in cell invasion." (PMID 25876034, 2015). "Furthermore, our data showed that TFF2 promotes colorectal cancer cell invasion by activating PAR4." (PMID 25876034, 2015). "Splenic denervation or deletion of TFF2 results in the expansion of MDSCs and colorectal cancer, indicating SVN-mediated splenic TFF2 expression plays essential role in the inhibition of MDSCs proliferation and immunosuppression." (PMID 32200357, 2020). "Expression of DCAMKL1 has been reported in mouse adenoma and human colorectal cancer, and thus DCAMKL1 and TFF2 are putative markers for gastric carcinogenesis." (PMID 20565818, 2010). "In colon mucosa, TFF2 was expressed with low intensity, but the expression of TFF2 in the progress of colorectal cancer was not clear." (PMID 25876034, 2015). "The mRNA and protein expression levels of PAR4 and TFF2 were remarkably increased in colorectal cancer compared with matched noncancerous tissues, especially in positive lymph node and poorly differentiated cancers." (PMID 25876034, 2015). "However, in patient tissues with colorectal cancer, after the samples were normalized to β-actin levels, a significant increased expression of PAR4 and TFF2 was observed in colorectal cancer tissues as compared with the matched nonmalignant tissues." (PMID 25876034, 2015). "In the study, we presented some fundamental data that the expression levels of PAR4 and TFF2 were significantly increased in colorectal cancer tissues when compared to the matched noncancerous tissues, especially in the metastatic positive lymph nodes and poorly differentiated tumors." (PMID 25876034, 2015).
colorectal cancer (continued). "In the study, we showed the expression levels of PAR4 and TFF2 were increased in colorectal cancer tissues when compared with the matched noncancerous mucosa, and the up-regulation expression of PAR4 in colorectal cancers may be resulted from the promoter hypomethylation." (PMID 25876034, 2015).
COVID-19 (7 papers, 2020 to 2024). A disease caused by infection with severe acute respiratory syndrome coronavirus 2. "Inhaled IFN-κ plus TFF2 therapy was investigated in one RCT on moderate COVID-19." (PMID 33391531, 2021). "We have previously tested this concept in SARS-CoV-2 infected patients during the first wave of the COVID-19 outbreak in 2020, and the results showed that the combination of TFF2 and human IFN kappa, one of the type I IFNs, is a highly safe and effective therapeutic for COVID-19." (PMID 36578554, 2022). "Based on these results, we hypothesized that the combination of TFF2 and human type I IFN is likely to synergistically fight against COVID-19 by reducing viral replication, alleviating the inflammatory response, and improving respiratory mucosal reconstruction." (PMID 36578554, 2022).
gastric tumor (7 papers, 2014 to 2023). "Methylation of TFF-2 promoter increases during gastric tumor advancement, and chronic H. pylori infection is associated with increased promoter methylation of TFF2 gene in the gastric mucosa." (PMID 30781778, 2019). "TFF2 methylation has been shown to inversely correlate with mRNA levels of TFF2 at the time of Helicobacter pylori infection and to increase throughout gastric tumor progression." (PMID 24765170, 2014). "After the samples were normalized to the β-actin level, a marked reduction or loss of TFF2 protein was observed in four gastric tumor tissue samples compared with the matched non-malignant tissues." (PMID 24765170, 2014). "We recently demonstrated that αGlcNAc serves as a tumor suppressor for gastric neoplasm including PGA, but the significance of TFF2 expression remains unknown." (PMID 38062108, 2023). "As with MUC1, TFF2 was significantly decreased in non-cardia and cardia tumor tissues compared with that in adjacent normal tissues (P = 4.00 × 10− 21 and P = 3.29 × 10− 14, respectively)." (PMID 32122390, 2020).
colon cancer (6 papers, 2014 to 2024). "We previously have shown that TFF2 gene delivery via adenovirus (Ad-Tff2) suppresses colon tumor growth in colitis associated cancer." (PMID 30042499, 2019). "Bilateral vagotomy reduces the expression of trefoil factor 2 (TFF2) in the spleen of mice, suggesting that cholinergic signaling enhances TFF2 release, which, in turn, inhibits the expansion of MDSCs and suppresses inflammation and colon cancer development." (PMID 39492832, 2024). "In colon cancer, cholinergic stimulation prevents colon cancer progression by inducing anti-inflammatory peptide trefoil factor 2 secretion from memory T cells to suppress MDSC expansion." (PMID 36077804, 2022). "To conclude, we identified two distinct qPCR gene expression profiles correlating with response (low expression of ALDH6A1 + TFF2 + MCM5) and with PFS (KLF12-high + TFF2-low) in advanced colon cancer patients managed with bevacizumab and chemotherapy." (PMID 24555920, 2014). "Transgenic overexpression of TFF2 or adenoviral delivery of TFF2 reduced myeloid proliferation and MDSC production, resulting in increased CD8+ T cells and decreased colon tumor growth." (PMID 30042499, 2019). "Vagus stimuli promote the secretion of trefoil factor 2 (TFF2), an anti-inflammatory peptide, from memory T cells, which leads to the suppression of myeloid cells and the alteration of the inflammatory microenvironment in colonic tumors." (PMID 31405140, 2019). "There was a significant accumulation of CXCR4-expressing MDSCs around colonic tumours (50- to 100-fold), along with increased expression of pro-tumorigenic cytokines IL-17A and IL-1β, in Tff2-null and wild-type mice compared with CD2–Tff2 mice." (PMID 26841680, 2016).
gastritis (6 papers, 2013 to 2025). Inflammation of the stomach. "Collectively, these findings suggest that the four biomarkers, namely, CHI3L1, FCGBP, VSIG2, and TFF2, hold the potential for diagnosing GC, particularly in cases of gastritis and early‐stage GC." (PMID 40084401, 2025). "Tff2-deficient mice (Tff2KO) show accelerated progression to H. pylori-induced gastritis, which is in line with the view that TFF2 stabilizes the gastric mucus barrier." (PMID 31801293, 2019). "Besides, previous experiments indicated that Tff2−/− mice promoted the progression of gastritis to dysplasia after H. pylori infection." (PMID 32122390, 2020). "In the stomach, the metaplastic cells that emerge upon parietal cell death express large amounts of trefoil factor 2 (TFF2; also known as spasmolytic polypeptide), so the cell lineage shifts in chronic atrophic gastritis have been called spasmolytic polypeptide expressing metaplasia (SPEM)." (PMID 30037967, 2018). "Overexpression of ShhWT induced gastritis (3/3 medium expressing mice) at medium Shh levels and gastric metaplasia only in the highest-expressing founder characterized by the co-localization of TFF-2 and intrinsic factor." (PMID 23520544, 2013).
lung disease (6 papers, 2018 to 2025). "Mounting evidence shows that TFFs have therapeutic potential in lung disease, and TFF2 promoted repair and had anti-apoptotic effects on epithelial cells in the lung." (PMID 35705945, 2022).
dysplasia (5 papers, 2013 to 2025). A usually neoplastic transformation of the cell, associated with altered architectural tissue patterns. "Genetically engineered mice deficient in TFF2 show a minimal phenotype, with only a slight reduction in proliferation rates in the gastric mucosa but H. pylori-infected TFF2-deficient mice develop more advanced premalignant lesions of atrophy, metaplasia, and dysplasia than WT mice." (PMID 24216700, 2013). "Specifically, during normal esophageal squamous, BE metaplasia, dysplasia, and EAC progression there is a progressive increase in TFF2, TFF3, MUC2, MUC5AC, MUC6, CDX2 with the development of intestinal metaplasia." (PMID 36994101, 2023).
gastric ulcer (5 papers, 2015 to 2026). An ulcerated lesion in the mucosal surface of the stomach. "Previous studies highlighted the ability of ethanol to decrease the expression of TFF-2 as well as halting the gene expression of MUC-6 in gastric ulcer in rats." (PMID 40775122, 2025). "TFF2, containing two trefoil domains, is believed to be the principal cytoprotective trefoil factor in the stomach, and the expression level of TFF2 was deregulated in gastric ulcer and cancer tissue." (PMID 25876034, 2015). "TFF2 modulation as a potential preventive strategy for ethanol-induced gastric ulcers." (PMID 41660303, 2026). "In a mouse model of ethanol-induced gastric ulcers, ORES downregulated TNF-α, IL-6, NF-κB, and COX-2 expression while upregulating trefoil factor 2 (TFF-2) expression, demonstrating significant anti-inflammatory and immunomodulatory effects." (PMID 39943187, 2025).
pneumonia (5 papers, 2020 to 2024). An acute, acute and chronic, or chronic inflammation focally or diffusely affecting the lung parenchyma, caused by an infection in one or both of the lungs (by bacteria, viruses, fungi, or mycoplasma.). "To investigate the detrimental effects of decreased splenic TFF2 after surgery on the function of immune defenses against pathogens, we induced primary pneumonia with Escherichia coli (E.coli)." (PMID 32200357, 2020). "A randomized clinical trial of 80 patients with moderate COVID-19 and pneumonia found that aerosol inhalation of IFN-ĸ (a type I IFN) combined with TFF2 anti-inflammatory polypeptide led to faster SARS-CoV-2 clearance and facilitated clinical resolution of pneumonia." (PMID 33375371, 2020).
adenoma (4 papers, 2010 to 2023). A neoplasm arising from the epithelium. "In addition, monomeric Tff2 could also reach the duodenum from the pancreas via the pancreatic duct and the ampulla of Vater, the latter being a prominent location for adenoma and carcinoma in humans." (PMID 37108221, 2023). "Thus, a reduction of the mucus barrier function by a reduced Tff2 level could favor permeation of microorganisms and chronic inflammation leading to adenomas in the antrum because this is the preferred region for microbial colonization in the stomach." (PMID 31963721, 2020).
asthma (4 papers, 2008 to 2022). "OVA induces 37 differentially expressed genes, with 14 of these genes also listed within the PM-regulated SAM list including the potent asthma bio-markers Clca3 and Tff2." (PMID 19057703, 2008). "It has been shown that inhalation of IFN-κ plus Trefoil factor 2 (TFF2) can promote the repair of airway epithelial cells exposed to injury, and significantly improves symptoms such as cough in asthma patients." (PMID 35782361, 2022).
cholangiocarcinoma (4 papers, 2012 to 2025). A carcinoma that arises from the intrahepatic biliary tree (intrahepatic cholangiocarcinoma) or from the junction, or adjacent to the junction, of the right and left hepatic ducts (hilar cholangiocarcinoma). "In this study, we aimed to identify and quantify a novel TFF2 splice variant in cholangiocarcinoma (CCA)." (PMID 22159958, 2012). "Trefoil factor 2 (TFF2), a gene encoding exocrine protein, was found to be specifically upregulated in pancreatic intraepithelial neoplasia and PC, with no significant expression observed in benign pancreatic diseases, cholangiocarcinoma, or hepatocellular carcinoma." (PMID 41040532, 2025). "Trefoil factor 2 (TFF2) is a member of trefoil factor family found to be overexpressed in many cancers including cholangiocarcinoma (CCA)." (PMID 22159958, 2012).
co-infection (4 papers, 2018 to 2025). "Here, we find that hookworm infection in a Brazilian cohort preferentially elevated TFF2 levels in females, even when compared to co-infection with Schistosomes or Schistosoma alone." (PMID 34662329, 2021). "Therefore, we sought to determine what effect co-infection of hookworm and Schistosoma, or either infection alone might have on TFF2, TFF3, and IL-33 levels in serum as compared to both endemic and non-endemic controls, accounting for age and sex as covariates." (PMID 34662329, 2021). "Overall, this indicates that TFF2 is elevated in Hookworm infected females, but not in Schistosoma or co-infection." (PMID 34662329, 2021). "TFF2 was specifically elevated by Hookworm infection in females, not Schistosoma or co-infection." (PMID 34662329, 2021).
ovarian carcinoma (4 papers, 2016 to 2023). A malignant neoplasm originating from the surface ovarian epithelium. "Despite displaying distinct protein expression patterns in ovarian carcinoma, Pearson correlation analysis revealed recurrent co-expression between TFF1/TFF2 and TFF1/TFF3." (PMID 36818673, 2022).
Barrett esophagus (3 papers, 2014 to 2017). Esophageal lesion lined with columnar metaplastic epithelium which is flat or villiform. "Moreover, consistent with the published report, we can demonstrate increased mRNA expression of the Barrett's esophagus associated genes Cckbr, Tff2, and Krt19 (data not shown)." (PMID 26460825, 2015). "The analysis of this mouse model of Barrett’s esophagus provided evidence that increasing stem cell marker LGR5 and niche cell marker DCLK1 and decreasing differentiation marker (secretory mucus cells, TFF2+ cells) correlated with a high tumor score." (PMID 28930282, 2017). "Low levels of TFF2 supported the best discrimination between nondysplastic Barrett’s esophagus and Barrett’s esophagus with cancer, followed by high levels of DCLK1, low goblet ratio and high LGR5 expression." (PMID 28930282, 2017).
clear cell carcinomas (3 papers, 2021 to 2024). "The diagnostic value of TFF1, TFF2 and TFF3 was then evaluated by immunohistochemistry on 206 stage I-II OCs stratified by histotype (high-grade serous carcinoma [HGSC], endometrioid carcinoma [EC], clear cell carcinoma [CCC], and MC)." (PMID 36818673, 2022). "A combination of HIK1083 and TFF2 testing can be useful, as TFF2 is expressed in 80% of gastric-type tumors compared with 12% of non–gastric-type tumors, with no clear cell carcinomas having been shown to be positive." (PMID 33570865, 2021). "A combination of HIK1083 and TFF2 testing can be useful because TFF2 is expressed in 80% of GAS cases compared with 12% of non-GAS cases, with no clear cell carcinomas showing positive results." (PMID 38366663, 2024).
Gastric Metaplasia (3 papers, 2013 to 2025). Intestinal metaplasia of the gastric mucosa is an intermediate precancerous gastric lesion in the gastric cancer cascade from chronic gastritis and atrophy to dysplasia and adenocarcinoma. "In addition, markers of gastric metaplasia, including Tff2, Cd44, and Clu, were upregulated in Arid1a-mutated SPGs, PPGs, and even mature pit cell clusters." (PMID 40761291, 2025).
Helicobacter infection (3 papers, 2017 to 2021). "Furthermore, TFF2 deficiency leads to a deregulation of macrophages’ and lymphocytes’ proliferative responses, and an accelerated gastritis progression during Helicobacter infection." (PMID 33494143, 2021). "Taken together, these data suggest that TFF1 is induced upon Helicobacter infection in both cellular systems, while TFF2 and TFF3 responses change depending on the host system." (PMID 29085807, 2017). "Indeed, Helicobacter infection upregulated it in gastric tissues, macrophages and lymphocytes, whereas Helicobacter pylori eradication decreased TFF2 level in patients’ sera." (PMID 33494143, 2021). "In IHC staining, TFF2 and MUC2 were both positive in epithelial cells after chronic Helicobacter infection." (PMID 29212456, 2017).
helminth infection (3 papers, 2018 to 2021). "While we were able to make advances by reporting infection, sex, and age-specific effects on TFF2 and TFF3 levels in human helminth infection, these studies do have some shortcomings that limit their interpretation." (PMID 34662329, 2021). "To further support the translational potential of TFFs as a biomarker of infection or therapeutic target, we evaluated the levels of TFF2 and TFF3 for the first time in human helminth infection in geographically distinct regions." (PMID 34662329, 2021).
nephrolithiasis (3 papers, 2013 to 2018). The presence of a calculus in the pelvis of the kidney; this is most often composed of mineral salts and proteins. "The same study described increased urinary TFF2 levels in patients suffering from nephrolithiasis and associated TFF2 upregulation during urinary tract infection by so far unpublished results." (PMID 28355260, 2017). "In the human urinary tract, TFF3 is detected as the most abundant form followed by TFF1, while urine TFF2 and TFF3 are increased in patients with nephrolithiasis." (PMID 29850501, 2018). "TFF2 has been demonstrated to be the predominant TFF peptide excreted in urine, and significantly increased urine TFF2 levels, together with occasionally increased TFF3 levels have been observed in patients suffering from nephrolithiasis." (PMID 24282531, 2013).
Splenomegaly (3 papers, 2016 to 2020). Abnormal increased size of the spleen. "However, on DSS treatment CD2–Tff2 mice showed insignificant expansion of CD11b+Gr-1+ IMCs, while Tff2-null mice had an exaggerated splenic IMC response with splenomegaly compare with wild-type and CD2–Tff2 mice." (PMID 26841680, 2016).
chronic kidney disease (2 papers, 2017 to 2019). Impairment of the renal function secondary to chronic kidney damage persisting for three or more months. "In addition, TFF2 serum concentrations were recently shown to increase in chronic kidney disease." (PMID 31817054, 2019). "Similarly, TFF2 upregulation in chronic renal failure might occur to limit cell death and epithelial damage." (PMID 28355260, 2017). "However, larger clinical studies and longitudinal surveys will be necessary to reveal the role of TFF2 as biomarker in CKD and during progression to end-stage renal disease in different renal diseases." (PMID 28355260, 2017). "In chronic kidney disease (CKD), TFF1 and TFF2 are reported to be upregulated." (PMID 28355260, 2017).